CD4 (CD4 molecule)
Diseases named in the same sentence as CD4 in open-access papers (continued):
Sharing a sentence is not in itself a finding about the gene and the disease.
Insulin resistance (continued). "Our working hypothesis underscores the conceivable role of PD-1+CD4 Tconv cells in effecting an inter-organ propagation of a proinflammatory milieu, thereby contributing to insulin resistance across various insulin-sensitive tissues." (PMID 38380252, 2024). "When Th1 statically overwhelms CD4+ FoxP3- Tregs, weight gain and insulin resistance are reversed." (PMID 36776877, 2023). "Moreover, insulin resistance (IR) and a change in receptors affect T cell function, specifically polyclonal CD4 cell activation and effector cytokine production, such as Th1 and Th17 cells." (PMID 36678282, 2023). "Moreover, the production of IFN-γ is dominated by CD4+ T cells, which are prone to Th1 cytokine profiles and related to leptin, insulin resistance, and NASH." (PMID 36552805, 2022). "We speculate that the beneficial effects of preoperative oral carbohydrate on postoperative NK%, CD3%, and CD4% were due to suppression of perioperative insulin resistance and hyperglycemia." (PMID 32309426, 2020). "Additionally, our group found recently that insulin resistance correlates significantly with a shift in the ratio of naïve and differentiated memory CD4+ and CD8+ T cells in abdominal subcutaneous adipose tissue in female obese subjects." (PMID 33349270, 2020). "Prior studies reported that feeding mice a diabetogenic HFD for at least a month increased the relative abundance of Peptostreptococcaceae, which was linked to lower upper gut Th17 responses, including lower RORγt CD4 T cells that provide protective immunity from diet-induced insulin resistance." (PMID 32860984, 2020). "In a recent study, intestinal RORγt+ IL-17+CD4+ T-cells were shown to participate in energy metabolism in mice, and specifically, a reduction of RORγt+ and IL-17-producing CD4+ T-cells contributed to the development of insulin resistance." (PMID 32082078, 2019). "This is suggested by the fact that genetic CD4 and CD8 T cell deficiency (TCRβ-/-) in diet induced obese mice resulted in attenuated adipose tissue and skeletal muscle inflammation and a protection from hyperglycemia and insulin resistance." (PMID 30949049, 2019). "Experimental models demonstrate that the adoptive transfer of CD4+ T cells into lymphocyte-free Rag1−/− mice reverses weight gain and insulin resistance, while depletion of CD8+ T cells in adipose tissue reduces macrophage density and improves insulin sensitivity." (PMID 30559739, 2018). "We also investigated the mechanism by which CD4+CD25+Foxp3+ Tregs decreases insulin resistance." (PMID 29541033, 2018). "Our inability to find a direct link between CD4 percent and insulin resistance may be related to the small sample size of our cohort." (PMID 24587328, 2014). "Crosstalk between pathogenic CD4 + and CD8 + T cells and CD11c + M1 macrophages in obese adipose tissue further enhances the inflammatory immune response induced by adipocyte apoptosis and macrophage infiltration, exacerbating adipose tissue inflammation and peripheral insulin resistance." (PMID 38468345, 2024). "Hence, the relationship between insulin resistance and CD4+ T cells is still unclear." (PMID 28651594, 2017). "Oral administration of the OKT3 antibody increases CD4+LAP+ and CD4+CD25+LAP+ Tregs populations, elevates serum TGF-β, significantly reduces AST, and improves insulin resistance and hepatic injury." (PMID 41394841, 2025). "The participants with insulin resistance had a significantly larger population of CD28 − CD57+ senescent T cells among the CD4+ and CD8 + T cells than those with lower Homeostatic Model Assessment for Insulin Resistance (HOMA-IR) values." (PMID 37735474, 2023). "Astaxanthin reduces the recruitment of CD4+ and CD8+ T cells in the liver, reverses insulin resistance, and liver inflammation and fibrosis, and has been shown more effective than vitamin E in the prevention and treatment of MASH." (PMID 37361209, 2023).
Insulin resistance (continued). "Administration of ADM to transgenic mice restored early insulin resistance in adipose tissue by inhibiting adipocyte major histocompatibility complex class II (MHC II) antigen presentation and CD4 (+) T cell activation." (PMID 34174798, 2022). "Through TH2 cell increases, CD4+ T cell transfer into HFD Rag1–/– animals reversed weight increase and insulin resistance." (PMID 32581740, 2020). "Adoptive transfer of these CD153+ PD-1+ CD44hi CD4+ T cells into lean mice on a normal diet induced inflammation in VAT, as well as insulin resistance." (PMID 30559739, 2018). "Given the massive increases of CD8+ T cells and conventional CD4+ T cells in aging adipose tissue and the discussed roles of T cells in metabolic functions, it is plausible that adipose tissue T cells may also contribute to age-related metabolic dysfunction and insulin resistance." (PMID 30619305, 2018). "Recent studies show that B cell-mediated CD4+ and CD8+ T cell activation is required to induce inflammation and insulin resistance." (PMID 23516375, 2013). "Application of β-cryptoxanthin helps to inhibit the recruitment of CD4+ and CD8+ T cells in the liver, attenuate insulin resistance and excessive lipid accumulation and peroxidation in the liver, and ultimately prevent or reverse inflammation and fibrosis in MASH." (PMID 37361209, 2023). "Functional studies have revealed that increased infiltration of both CD4+ and CD8+ T cells could facilitate insulin resistance development, probably through modulating vascular regeneration." (PMID 37305035, 2023). "Unlike CD4+ regulatory T cells, CD8+ T and CD4+ T helper one counterparts promoted insulin resistance." (PMID 36276976, 2022). "In conclusion, in well-treated PLWH with absence of chronic hepatitis B or C infection, insulin resistance was associated with abdominal obesity, exposure to older generation ART, and CD4+ nadir < 200 cells/μL." (PMID 35643429, 2022). "Interestingly, within the VAT, CD4+ T cells adopt a senescent phenotype which drives VAT inflammation and insulin resistance in an osteopontin dependent manner." (PMID 32499756, 2020). "Moreover, the percentages of naïve CD4+ and CD8+ T cells were significantly higher, whereas activated T cells and IL-6 levels were lower in IS compared to insulin resistant (IR) obese individuals." (PMID 33349270, 2020). "The percentage of peripheral CD4+CD25+Foxp3+ Tregs is decreased in the patients with type 2 diabetes mellitus and the accumulation of Tregs in adipose tissue plays an important role in reducing obesity related insulin resistance in mice." (PMID 29541033, 2018). "Moreover, astaxanthin caused an M2-dominant shift in macrophages/Kupffer cells and a subsequent reduction in CD4+ and CD8+ T cell recruitment in the liver, which contributed to improved insulin resistance and hepatic inflammation." (PMID 26603489, 2015). "CD4+ and CD8+ T cells infiltrate obese human adipose tissue and induce local and systemic inflammation with an increased production of proinflammatory cytokines and provide a major link to the pathogenesis of insulin resistance." (PMID 25013207, 2014). "Foxp3+CD4+ regulatory T cells (Treg), anti-inflammatory IL-10 producer, are unique cell population that suppresses inflammation, and Treg cells are decreased in HFD-induced and genetically modified obese mice resulting in insulin resistance." (PMID 23781214, 2013). "CD4+ T cells in adipose tissues of obese rodents and humans mediate HFD-induced insulin resistance." (PMID 23781214, 2013). "Higher leukocyte count, including monocyte and CD4+ T cell count, has been found in SIRD and MOD patients compared to SIDD and MARD patients, suggesting that specific dysregulation of immune cells may closely relate to insulin resistance in these groups." (PMID 37305035, 2023).
Insulin resistance (continued). "Mice with global deficiency of MHC-II demonstrate protection from adipose tissue inflammation and systemic insulin resistance when placed on a HFD; the accumulation of CD4+ T cells and reduction in CD11c+ macrophages may be responsible for the reduced adipose tissue inflammation in these animals." (PMID 30559739, 2018). "Dysregulation of CD4+CXCR5+ T cells and production of excessive proinflammatory cytokines may play an important part in the mechanism of chronic low-grade inflammation of insulin resistance." (PMID 28926600, 2017). "The absence of CD4+ T cells in murine MASH significantly reduces hepatic injury, inflammation, and fibrosis, independent of insulin resistance or liver steatosis." (PMID 40631180, 2025). "Indeed, senescent-associated CD153+CD4+ T-cells from obese mice have been reported to drive metabolic dysregulation and inflammation within the VAT—where their adoptive transfer into non-obese mice induced insulin resistance and pro-inflammatory cytokine production in the recipient mice." (PMID 36891817, 2023). "However, the expression of IFN-γ in senescent CD4+ and CD8 + T cells was not related to the insulin resistance status of the participants with T2D." (PMID 37735474, 2023).
liver cancer (110 papers, 2009 to 2025). An epithelial or non-epithelial malignant neoplasm that arises from the liver. "Triple infection with HIV/HBV/HDV was associated with significantly lower CD4+ cell counts and worse clinical outcomes, including elevated liver enzymes and rapid progression to liver cancer." (PMID 39599836, 2024). "In patients with hepatitis B virus (HBV)‐associated primary liver cancer, the counts of T lymphocytes, natural killer cells, B cells, CD4+ T cells and CD8+ T cells were all decreased compared to those chronic hepatitis B infection." (PMID 38826094, 2024). "NK cells and CD4+T cells have been proven to play important roles in liver cancer and are associated with various treatment outcomes." (PMID 37596654, 2023). "Next, we further found that the mRNA expression of all LILRB family members was significantly associated with the infiltration of B cells, CD8+ T cells, CD4+ T cells, macrophages, neutrophils, and dendritic cells in liver cancer." (PMID 35321724, 2022). "People with HIV coinfected with hepatitis B virus and/or hepatitis C virus, those with higher HIV RNA levels and lower CD4 cell counts, and persons who inject drugs had a higher liver cancer risk." (PMID 33595662, 2021). "For liver cancer, the association between the CD4 count at the time of cancer diagnosis and mortality risk was next to threshold for statistical significance (p = 0.05)." (PMID 24760049, 2014). "To determine the role of ChAT-expressing T cells in the onset of liver cancer, we deleted Chat specifically in T cells by crossing mice carrying the conditional Chatfl allele with mice expressing the Cd4-cre transgene, thereby obtaining Chatfl/fl; Cd4-cre progeny." (PMID 37640929, 2023). "Moreover, nine activated memory CD4 T cell-related genes were associated with liver cancer prognosis [e.g., eomesodermin (EOMES), glutathione S-transferase (CST7), and adhesion G protein-coupled receptor E2 (EMR2)]." (PMID 34980144, 2022). "The loss of granzyme B-expressing CD4+ T cells predicted poor survival in liver cancer." (PMID 34631551, 2021). "And a novel insight is that immunophenotypes of CD3 on naive CD8+ T cells and CD3 on naive CD4+ T cells were revealed as mediators of the association between anilides and the risk of liver cancer, which may be a potential molecular mechanism for PAU’s protective effect against liver cancer." (PMID 39062110, 2024). "Previously, CST7 has also been associated with CD4(+) T cell and CD8 (+) T cell activation in liver cancer." (PMID 39851522, 2025). "In liver cancer, CD4+ and CD8+ T cells localize primarily in the peritumoral zone, with tumor-infiltrating antigen-specific CD8+ T cells playing a key role in immune response and cancer control." (PMID 40136652, 2025). "A study on liver cancer patients with percutaneous thermal ablation found that the peripheral blood of patients with early recurrence contained a high proportion of PD-1+CD4+ T cells and TIM-3+CD8+ T cells." (PMID 38833177, 2024). "For instance, CD4+ T cells can eliminate senescent hepatocytes before liver cancer develops in mice and inhibit mouse liver cancer." (PMID 39122450, 2024). "The subsequent two-step MR mediation analyses demonstrated that the protective effect of anilides on liver cancer risk is partially mediated by increased immunophenotypes of CD3 on naive CD8+ T cells and CD3 on naive CD4+ T cells." (PMID 39062110, 2024). "For liver cancer, only the CD4 count in unvaccinated individuals was significantly lower than that in vaccinated patients." (PMID 38826094, 2024). "Another scRNA-seq-based study found the presence of CD4+ CTLs coexpressing Gzmb and Nkg7 in bladder and liver cancers." (PMID 38515134, 2024). "These genes inhibited the proportion of B cell, CD8 + cell and CD4 + cell in the immune potential environment of liver cancer." (PMID 39083127, 2024). "Another scRNA-seq-based study found CD4+ CTLs coexpressing Gzmb and Nkg7 in bladder and liver cancers." (PMID 38515134, 2024).
liver cancer (continued). "Specifically, SLC10A3 plays a critical role in regulating the immune response in liver cancer, related with stromal CD4 T cells, CD20 B cells, and macrophage." (PMID 38178258, 2024). "When we subjected these animals (and Chatfl/fl controls) to HCC induction, we found that Chatfl/fl; Cd4-cre mice developed liver cancer much faster than their Chatfl/fl littermates." (PMID 37640929, 2023). "In this study, we establish that subpopulations of CD4+ T cells expressing choline acetyltransferase (ChAT), the rate-limiting enzyme governing ACh synthesis, are induced during the development of liver cancer in mice." (PMID 37640929, 2023). "We analyzed and visualized the major cell type of liver cancer, with conventional CD4+ T cells accounting for a large proportion of the HCC immune microenvironment." (PMID 36700197, 2022). "Our study demonstrated that CD4+ T cells were positively correlated with the prognosis of patients with liver cancer." (PMID 35321670, 2022). "CD4+ T lymphocytes have been reported to inhibit the development of liver cancer and mediate tumor regression." (PMID 35027925, 2022). "For instance, CD4+ memory static T cells inhibit the development of liver cancer and media for tumor retreat." (PMID 36686655, 2022). "We found that LAIR1 expression was generally highly correlated with CD33 (a marker for myeloid cells) and CD4 (a marker for T cells) in most cancers except liver cancer." (PMID 36211388, 2022). "More specifically, this expression was positively correlated with the immune infiltration of B cells, CD8+ T cells, CD4+ T cells, macrophages, neutrophils, and dendritic cells in patients with liver cancer." (PMID 33439969, 2021). "CD4+ T cell patients with high expression of ZIC2 mRNA in liver cancer had a better 5-year survival prognosis, as analyzed through the Timer database." (PMID 33439969, 2021). "CD4+CD25+CD127lowTregs in peripheral blood of patients with liver cancer in those≤ 49 years old (6.21±1.53%) were significantly higher than those in health subjects with the same age (3.30±1.45%; P<0.05)." (PMID 32218692, 2020). "CD4+CD25+CD127lowTregs in peripheral blood of patients with liver cancer in those≥50 years old (6.69±1.53%) were significantly higher than those in health subjects with the same age (4.69±1.27%; P<0.05)." (PMID 32218692, 2020). "Accordingly, we found that HSD17B6 expression in liver cancer was significantly negatively correlated with multiple immune cell infiltration, such as dendritic cells, CD4+ T cells, and B cells." (PMID 32514254, 2020). "We analyzed published CD4+ human liver cancer TIL (TILHLC) scRNA-seq data pooled across six treatment-naive patients." (PMID 31801070, 2019). "Conversely, senescence within premalignant hepatocytes induced CD4+ T-cell-mediated clearance and thus limited liver cancer development." (PMID 27272654, 2016). "CD8+ lymphocytes promote the killing of tumor cells, whereas regulatory CD4+ T cells potentially promote the progression of liver cancer." (PMID 24788770, 2014). "The increased glucose metabolism in CD4+ T cells suppresses liver cancer cell proliferation." (PMID 40122853, 2025). "Additionally, it can inhibit the proliferation and activation of CD4+ T cells in vitro, which promotes liver cancer." (PMID 40122853, 2025). "Specifically, the lower number of CD3+T cells and a higher ratio of CD4/CD8 in vaccinated patients with liver cancer suggest that the un‐coordinated immune response may impair the adaptive immune response to omicron." (PMID 38826094, 2024). "Similarly, adoptive allogeneic γδ T cell therapy in late-stage lung and liver cancer patients improved the frequencies of immune cells such as CD4+, CD8+, and Vδ2 γδ T cells." (PMID 39195212, 2024). "HSYA inhibits the levels of the CD4+CD25+FOXP3+ Tregs/CD4+T lymphocytes in liver cancer cells." (PMID 39877386, 2024).